NGF (nerve growth factor)
Diseases named in the same sentence as NGF in open-access papers (continued):
Sharing a sentence is not in itself a finding about the gene and the disease.
retinopathy (12 papers, 2014 to 2025). "Pharmacological studies demonstrate that NGF applied as eye-drops (ed-NGF) can reach the posterior segment of the eye and counteract the loss of retinal cells in animal model of retinopathy." (PMID 34576177, 2021). "We studied the role of NGF in the context of proliferative retinopathies by using the mouse ROP model." (PMID 30680928, 2019). "We found increased NGF staining in Muller cells in 18-month-old OXYS rats (progressive stage of retinopathy)." (PMID 30871541, 2019). "Alternation in NGF levels has been correlated with various diabetic microvascular complications including retinopathy, nephropathy, and neuropathy." (PMID 26807305, 2015). "Growing data indicate that NGF provides a potential approach in the treatment of retinopathies, characterized by RGCs death and following optic nerve degeneration." (PMID 24627687, 2014). "Our findings therefore indicate that NGF may represent a potential target for proliferative retinopathies." (PMID 30680928, 2019). "Our findings reveal an anti‐apoptotic role of NGF in the hypoxic retinal endothelium, which is involved in promoting pathological retinal vascularization, thereby pointing to NGF as a potential target for proliferative retinopathies." (PMID 30680928, 2019). "In human dermal microvascular endothelial cells, one report showed that Ngf-encoded protein treatment enhanced cell proliferation, and other study showed that in hypoxic retinal endothelium, NGF attenuated cell apoptosis, and may be as a potential target for proliferative retinopathies." (PMID 32285918, 2020). "Vimentin and NGF expression patterns were often colocalized in the cells of the GCL and in Muller processes across the plexiform layers in OXYS rats at the age of 18 months, suggesting that glial cells accumulate NGF during progressive stages of retinopathy." (PMID 30871541, 2019).
brain diseases (10 papers, 2020 to 2024). "Depletion of endogenous NGF in the brain leads to severe neurodegeneration and is a cause of various brain disorders often associated with cognitive dysfunction." (PMID 33375672, 2020). "This comprehensive review aims to synthesize current knowledge regarding the multifaceted roles of NGF brain disorders, traumatic brain injury, ophthalmology, and oncology, focused on the pediatric age." (PMID 39056738, 2024). "The pro-survival and regenerative properties of neurotrophic factors propose a therapeutic potential in a wide range of brain diseases, and NGF, in particular, has appeared as an encouraging potential treatment." (PMID 39056738, 2024). "While historically studied in the context of neurodevelopment and neurodegeneration in adults, emerging research has highlighted the significance of NGF across a broad spectrum of pediatric brain disorders, traumatic brain injury (TBI), ophthalmology, and oncology." (PMID 39056738, 2024). "NT-3 or NT4/5 are less discussed in the pathogenesis of brain disorders than NGF or BDNF." (PMID 34827728, 2021). "Therefore, in this section, we will discuss cardiovascular dysfunction related to NGF- or BDNF-compromised brain diseases, such as AD or Parkinson’s disease (PD)." (PMID 34827728, 2021). "We discuss how BDNF, NGF, IGF-1, and LIF could potentially be used for the treatment of brain diseases." (PMID 39598254, 2024).
inflammation (10 papers, 2006 to 2024). Aberrant reaction of the microcirculation characterized by movement of fluid and leukocytes from the blood into extravascular tissues. "Chronic neural plasticity due to unresolved bladder inflammation and sensory receptor activation may increase afferent activity by influencing antinociceptive activity and cause increases in nerve growth factor (NGF) levels and bladder oversensitivity." (PMID 36548734, 2022). "Some mast cell mediators are produced upon activation, namely, important growth factors in neurogenic inflammation [such as, the nerve growth factor (NGF)] and cytokines with relevance in cutaneous inflammation (such as, IL-1, IL-6, IL-18, IL-31 TNF-alpha)." (PMID 35387041, 2021). "In animal models of intestinal inflammation and in the colon and DRGs of CD patients, locally released nerve growth factor (NGF) and prostaglandins were shown to upregulate TRPV1 with a converging mechanism." (PMID 31370176, 2019). "In conclusion, our results suggest that NGF exacerbated the effects of OVA sensitization (airway inflammation, remodeling and hyperresponsiveness) via Th2 and MMP-9 pathways." (PMID 24223654, 2013). "Our results showed that NGF significantly increased eosinophilic airway inflammation, persistent airway hyperresponsiveness (AHR), the serum levels of OVA-specific IgE and the levels of Th2 cytokines in the BAL fluid, and also increased the expression levels and activity of MMP-9." (PMID 24223654, 2013). "Neurotrophin, a nerve growth factor (NGF), is responsible for mediating prostatic neurogenic inflammation." (PMID 31546892, 2019).
cardiovascular diseases (7 papers, 2009 to 2024). "In our study, the presence of rs1801282 CG/GG genotype was associated with low serum levels of HGF and NGF, possibly due to the effect of Ala variant on the decreased expression of PPARγ2 gene, which decrease the process of inflammation and cardiovascular disease." (PMID 25159899, 2014). "The protective effect of exogenous NGF during this systemic circulatory disease seems to occur also by strengthening the effect of endogenous NGF, the synthesis of which is increased by vascular defect and also by the mechanical lesion associated with NGF or even vehicle intraocular delivery." (PMID 19473529, 2009).
hematological malignancies (6 papers, 2017 to 2025). "Activation of pro-survival signaling by the NGF/TRKA axis has previously been associated with treatment resistance in hematological malignancies 42-44 lending support to the idea of employing TRKA inhibitors." (PMID 33456567, 2021). "Pro-survival TRKA/NGF signaling is associated with therapy resistance in hematological disorders." (PMID 34944554, 2021). "This study shows that the depletion of NGF occurs during the development of CIPN in patients with hematologic malignancy." (PMID 28827818, 2017). "However, the relationship between NGF level and CIPN in patients with hematologic malignancies remains elusive." (PMID 28827818, 2017). "A prospective study of 45 patients with hematologic malignancies treated with bortezomib, thalidomide, or vincristine, also found there was a significant decrease in NGF in participants who developed CIPN symptoms, whereas there was no change in NGF in participants who did not develop CIPN symptoms." (PMID 35360655, 2022).
immune diseases (6 papers, 2012 to 2025). "In particular, NGF stimulates B-cell proliferation and antibody production so that its upregulation in inflammatory and immune diseases has been linked to more severe clinical presentation." (PMID 37998739, 2023).
neurodevelopmental disorder (5 papers, 2022 to 2025). A behavioral and cognitive disorder with onset during the developmental period that involves impaired or aberrant development of intellectual, motor, or social functions. "In animal models, maternal infection alters BDNF and NGF expression in the fetal brain and maternal–fetal unit, potentially affecting synaptic development and increasing the risk of neurodevelopmental disorders." (PMID 40943255, 2025). "Neurotrophins, particularly BDNF and NGF, are key modulators of brain development and synaptic plasticity, and their dysregulation has been implicated in several neurodevelopmental disorders, including ASD, ADHD, ID, and tic disorders." (PMID 40943255, 2025). "Another commonly observed decrease in neurodevelopmental disorders is the Brain Nerve Growth Factor (NGF) level." (PMID 39329976, 2024). "Given this functional overlap, strategies aimed at enhancing neurotrophin signaling, whether through the modulation of BDNF/NGF or augmentation of FGF, EGF, IGF-1, and HGF activity, may have complementary effects in neurodevelopmental disorders." (PMID 40943255, 2025).
renal disorders (5 papers, 2013 to 2024). "NGF, a protective factor overexpressed in the kidney of various renal disorders, was elevated in podocytes of IgAN." (PMID 33936064, 2021). "Similarly, increased levels of NGF, a complex of 3 subunits—aNGF, bNGF, and gNGF, has been reported in the sera of SLE patients and various renal disorders." (PMID 29026368, 2017).
central nervous system diseases (4 papers, 2016 to 2025). "Nerve growth factor(NGF) is a powerful neurotrophic protein fortreating central nervous system diseases, but its therapeutic utilityis limited by severe side effects, including hyperalgesia." (PMID 40893961, 2025). "Evidence has been found which supports the therapeutic properties of NGF on cutaneous cells, cells of the visual system, and certain diseases of the central nervous system." (PMID 34208522, 2021).
metabolic disorders (4 papers, 2014 to 2025). "The HGF and NGF are considered adipokines with a possible link to metabolic disorders and other inflammatory-related diseases." (PMID 25159899, 2014).
urological disorders (4 papers, 2012 to 2022). "As NGF is associated with the development of urological disorders, reduced NGF expression and release could be part of BoNT/A mediated alleviation of symptoms of OAB patients." (PMID 35051030, 2022). "There are several studies in humans on NGF as a urinary biomarker showing increased NGF levels in patients with urinary tract disorders." (PMID 26746899, 2016). "The circulating inflammatory biomarkers such as NGF or BDNF might be the underlying pathophysiology of mixed urological disorders and non-urological diseases." (PMID 23028581, 2012). "Although no data exist on NGF or its p75 receptor in BE, our results are in line with investigations showing increased NGF expression of the unclosed bladder wall in patients with other painful urological disorders." (PMID 33692976, 2021).
cardiac diseases (3 papers, 2009 to 2021). "Although alteration in the level of NGF has a great impact on the clinical outcome in heart disease, the molecular mechanisms underlying the regulation of NGF expression and sympathetic innervation are poorly understood." (PMID 21037846, 2009).
bone cysts (2 papers, 2024 to 2025). "Furthermore, the elevated NGF expression was also associated with subchondral bone cysts." (PMID 39176036, 2024). "NGF plays an important role in skeletal physiology and pathology and is an important target for the treatment of skeletal diseases." (PMID 40860871, 2025). "Among them, there are many keywords related to NGF, such as Bone homeostasis, Bone formation, Bone resorption, Skeletal diseases and so on." (PMID 40860871, 2025). "In the future, the application of NGF in the treatment of skeletal diseases will be more promising with the deepening of related research and the expansion of clinical applications." (PMID 40860871, 2025).
gastrointestinal disorders (2 papers, 2015). "However, adverse events such as gastrointestinal disorders were likely caused by corticosteroids rather than NGF." (PMID 25574223, 2015).
respiratory diseases (2 papers, 2022 to 2023). "The aim of this study was to measure the short-term effects after exposure to side-stream smoke on Nerve Growth Factor and its receptors Tropomyosin-related kinase A and neurotrophin p75, molecules already described in health conditions and respiratory diseases." (PMID 36011952, 2022).
digestive system neoplasm (1 paper, 2025). A neoplasm (disease) that involves the digestive system. "In this review, we focused on recent and previous mechanistic studies and clinical trials of NGF, especially the role of NGF in the crosstalk between nerve cells and malignant cells such as digestive system neoplasms." (PMID 40783715, 2025).
functional intestinal disorders (1 paper, 2019). "More importantly, there is an upregulation of NGF and TRKA in colonic mucosal tissues from IBS patients, suggesting the relevance of NGF/TrkA signaling in functional intestinal disorders." (PMID 30988299, 2019).
gastrointestinal disease (1 paper, 2019). A disease that occurs in the gastrointestinal system, excluding the hepatobiliary system. "Our findings along with other previous studies therefore suggest that chronic exposure to NGF overexpression may be detrimental to health and increases risks for gastrointestinal diseases, such as IBS and intestinal-type cancers." (PMID 30988299, 2019). "Taken together, these findings suggest that NGF/Trk-A signaling may be a worthwhile therapeutic target in the management of pathophysiological phenotypes in gastrointestinal diseases." (PMID 30988299, 2019). "Inhibition of NGF may be an important therapeutic strategy for the treatment of gastrointestinal diseases, especially for IBS." (PMID 30988299, 2019).
nervous system neoplasm (1 paper, 2025). A neoplasm (disease) that involves the nervous system. "In addition to nervous system neoplasms, NGF is involved in the malignant transformation of other tissue cells, partly via nerve fibres and their secretory proteins near primary and metastatic cancerous lesions." (PMID 40783715, 2025).
overlap syndrome (1 paper, 2010). "In contrast, serum NGF levels were similar in patients with dSSc (346.16±210 pg/mL), lSSc (271.4±136.5 pg/mL) and overlap syndrome (195.5±52 pg/mL)." (PMID 21085492, 2010).
primary dysmenorrhoea (1 paper, 2017). "Here, Li and colleagues identify common variants in ZMIZ1 and near NGF conferring risk for primary dysmenorrhoea using genome-wide association study in a Chinese population." (PMID 28447608, 2017). "We identified two susceptibility loci in ZMIZ1 and near NGF for primary dysmenorrhoea, and provided further genetic evidence for the polygenic nature of primary dysmenorrhoea." (PMID 28447608, 2017). "Previous researches demonstrated obvious immunological functions for both ZMIZ1 and NGF, suggesting a potential role for the immune system in the pathogenesis of primary dysmenorrhoea." (PMID 28447608, 2017). "In summary, we present the first GWAS for primary dysmenorrhoea in Chinese population and identify two GWS loci (ZMIZ1 and NGF)." (PMID 28447608, 2017).
reproductive system diseases (1 paper, 2026). "It highlights NGF' dual functions as a central regulator of follicular dynamics, and as a potential biomarker and therapeutic target for common reproductive system diseases." (PMID 42194047, 2026).
NGF also shares sentences with these, for which no sentence is quoted: diabetic polyneuropathy (11 papers); Parkinson’s (10); genetic disorder (6); chronic prostatitis (4); coronary atherosclerosis (4); adenocarcinoma (3); chondropathy (3); fibrosis (3); gestational diabetes (3); Hip Osteoarthritis (3); hyperreactivity (3); type 1 diabetes (3); acute coronary syndrome (2); acute myeloid leukemia (2); autoimmune hyperthyroidism (2); benign tumors (2); chronic headache (2); Cicatricial Pemphigoid (2); cystic ovaries (2); Dysmenorrhea (2); endothelial dysfunction (2); erectile dysfunction (2); hereditary sensory and autonomic neuropathy type 4 (2); mental retardation (2); multiple myeloma (2); osteoarthropathy (2); pancreatic disease (2); primary open angle glaucoma (2); prurigo nodularis (2); Skin ulcer (2).
A further 133 diseases each share a sentence with NGF in 2 papers or fewer.